IL13 (interleukin 13)
Diseases named in the same sentence as IL13 in open-access papers (continued):
Sharing a sentence is not in itself a finding about the gene and the disease.
bladder cancer (9 papers, 2011 to 2025). "In the context of BCG therapy, our previous investigations in patients also suggested a potential role for ILC2s in bladder cancer recurrence, possibly through IL-13 secretion and MDSC recruitment." (PMID 38283350, 2023). "Another study showed that ILC2s facilitated tumor recurrence via the accumulation of MDSC by upregulating IL-13 among patients with bladder cancer." (PMID 34194433, 2021). "Expression of IL-13 in tumor cells has been studied in patients with bladder cancer at various stages of clinical malignancy and patients with benign bladder tumors." (PMID 33343662, 2020). "The ILC2/IL-13 axis modulates T cell-to-MDSC balance to drive an immunosuppressive microenvironment, whereas the inhibition of ILC2/IL-13 axis improves bladder cancer treatment." (PMID 32117199, 2019). "In addition, ILC2s enhanced the accumulation of myeloid-derived suppressor cells (MDSCs) by upregulating IL-13, which was involved in the recurrence of bladder cancer." (PMID 34194433, 2021). "Basophils may have a role in BCG-treated bladder cancer patients because of their ability to facilitate Th2 polarization by secreting proinflammatory interleukins (IL-4 or IL-13) and skewing antigen-presenting cells towards a type 2 response." (PMID 33343662, 2020). "A role for IL13 in human bladder cancer has not been determined as yet." (PMID 22013484, 2011).
fungal infection (9 papers, 2017 to 2025). "Anti-inflammatory cytokines such as IL-3, IL-4, IL-5, IL-9, IL-10, and IL-13 were also induced within 3 h of fungal infection in all three groups of mice and remained high up to the 7th day period." (PMID 38783167, 2024). "Cytokines involved in granuloma development, primarily IL-33, IL-5, and IL-13 were evaluated considering previous data on fungal infections." (PMID 34829225, 2021). "Meanwhile, anti-inflammatory cytokine IL-10 and type 2 cytokines (IL-4, IL-5, and IL-13) were similar in the WT or CD146 KO mice with fungal infection." (PMID 33537006, 2020). "Aside from the expected resistance of both IL-4 and IL-13 against fungal species, IL-4 takes part in the optimal development of IL-12-dependent Th1 responses and IL-13 increases oxidative burst and phagocytosis during fungal infections." (PMID 38058517, 2023).
liver disease (9 papers, 2015 to 2025). "In particular, IL-13 is able to promote hepatic fibrogenesis of different etiologies and has been identified as a major pathogenic cytokine in helminth-induced liver disease." (PMID 32846954, 2020). "Additionally, liver diseases are associated with the accumulation of hepatic natural killer (NK) cells, which produce IL-4 and IL-13." (PMID 41042784, 2025). "IL-13 is capable of promoting hepatic fibrogenesis of various etiologies and has been identified as a major pathogenic cytokine in helminth (schistosome)-induced liver disease." (PMID 37629063, 2023). "Their secretion of IL-13 and amphiregulin suggests they may be recruited to promote resolution and repair and thereby they may contribute to ongoing fibrogenesis in liver disease." (PMID 29261670, 2017).
malignant glioma (9 papers, 2012 to 2024). A grade III or grade IV glioma arising from the central nervous system. "Recombinant adenovirus, which expressed IL-13 on its surface, transferred genes to IL-13Rα2-expressing malignant glioma cells more effectively." (PMID 33450900, 2021). "Overall, IL-13-based toxins can be potentially used in adjuvant therapy for malignant gliomas, but their use requires further clinical studies." (PMID 22530127, 2012). "A phase III study was conducted to compare the efficacy of IL-13-PE to that of Gliadel wafers in patients with malignant gliomas." (PMID 22530127, 2012). "An interesting strategy utilizing convection-enhanced delivery (CED) to infuse GBM cells with a recombinant form of IL-13 fused to Pseudomonas Exotoxin A (IL13-PE38QQR) was evaluated in a phase 1/2 clinical trials for the treatment of patients with recurrent malignant gliomas (NCT00041587)." (PMID 36186781, 2022). "Convection-enhanced delivery of IL-13-PE was well-tolerated by patients with malignant gliomas." (PMID 23421960, 2013). "Liposomes, nano-sized artificial vesicles that can be loaded with drugs, when modified with IL-13, effectively deliver drugs to malignant glioma cells, showing superior efficacy compared to non-targeted delivery." (PMID 38201655, 2024).
metabolic syndrome (9 papers, 2017 to 2024). A cluster of metabolic risk factors for CARDIOVASCULAR DISEASES and TYPE 2 DIABETES MELLITUS. "Previous studies have shown that metabolic syndrome is exacerbated in IL-5 or IL-13 deficient mice that were placed on a HFD." (PMID 32948777, 2020). "Disease progression in chronic HBV infection leads to metabolic syndrome and chronic inflammation, with IL-13 playing a critical role in connecting the metabolic and inflammatory components." (PMID 36405584, 2022). "For four tested variables, VAI, IL-13, adiponectin and leptin AUC was low, which did not render these factors valuable as diagnostic indicators of the metabolic syndrome in our group." (PMID 36596839, 2023). "Further clinical research is needed to understand whether low and high-IL-13 producers have different risks for developing metabolic syndrome and its cardiovascular comorbidities." (PMID 29675435, 2018). "Moreover, metabolic syndrome subjects exhibit increased serum IL-13 that is also correlated with rising concentration of blood sugar and triglycerides." (PMID 29675435, 2018). "For example, lower levels of anti-inflammatory cytokines, including IL-4, IL-13, and IL-10, have been found in obese subjects with metabolic syndrome compared to those without metabolic syndrome." (PMID 36313072, 2022). "In fact, a recent study conducted in morbidly obese men with metabolic syndrome showed a significant increase in the serum levels of IL-6 and IL-12, both cytokines with proinflammatory actions, without reporting any difference in IL-13." (PMID 29675435, 2018). "Similarly, in absence of IL-5 or IL-13, metabolic syndrome is exacerbated in mice fed a HFD." (PMID 30755607, 2019). "Moreover, ninety percent of high-IL-13 producers had central obesity and hyperglycemia, while a similar amount also showed triglyceride levels higher than 200 mg/dl (data not shown), which suggests that increased IL-13 could concur with the development of metabolic syndrome." (PMID 29675435, 2018).
pulmonary hypertension (9 papers, 2009 to 2024). Increased pressure within the pulmonary circulation due to lung or heart disorder. "We also noted that IL-6 and IL-13 levels were increased in patients with pulmonary hypertension, and that TNFα levels were associated with the presence of renal crisis." (PMID 19799786, 2009). "It has been reported that transgenic expression of IL-13 in the lung of mouse, the T-helper type 2 cell effector cytokine, causes pulmonary arteriole remodeling and subsequently pulmonary hypertension, which is associated with enhanced expression of both Arg-I and Arg-II in the lung." (PMID 23781221, 2013). "Pulmonary hypertension were observed in mice exposed to inhaled Aspergillus193 and in IL-13–overexpressing mice developed pulmonary hypertension." (PMID 31024947, 2019). "Potential conclusion: IL-13 promotes the development of pulmonary hypertension via an IL-13 - IL-13Rα2 - Arg2 pathway leading to an imbalance of NO homeostasis and increased muscularization of pulmonary arteries." (PMID 24739042, 2014). "Genetic deletion of Arg-II gene in this mouse partly prevents IL-13-induced pulmonary hypertensive phenotypes, suggesting the involvement of Arg-II." (PMID 23781221, 2013). "Patients with pulmonary hypertension were more likely to have higher IL-6 (odds ratio = 1.31, 95% confidence interval = 1.04 to 1.67) and IL-13 (odds ratio = 1.42, 95% confidence interval = 1.04 to 1.94)." (PMID 19799786, 2009). "Lastly, patients with interstitial lung disease had elevated IL-6 and patients with pulmonary hypertension had elevated IL-6 and IL-13." (PMID 19799786, 2009). "However, the experimental data show both protective and deleterious effects of IL-13 and it is too early to make conclusions on the potential use of IL-13 and its pathways as therapeutic target for pulmonary hypertension." (PMID 24739042, 2014). "Importantly, a key role of Th2 inflammation in the pathogenesis of pulmonary hypertension has been demonstrated in lung-specific IL-13-overexpressing mice, which develop spontaneous pulmonary hypertension, pulmonary arterial remodeling, and right ventricular hypertrophy." (PMID 35757687, 2022). "IL-13 was elevated in the plasma of patients with systemic sclerosis with pulmonary arterial hypertension compared with patients without pulmonary arterial hypertension." (PMID 31024947, 2019).
vitamin D deficiency (9 papers, 2013 to 2025). A nutritional condition produced by a deficiency of VITAMIN D in the diet, insufficient production of vitamin D in the skin, inadequate absorption of vitamin D from the diet, or abnormal conversion of vitamin D to its bioactive metabolites. "Unlike the uniformly risk-amplifying effects of Th2-pathway variants (IL4R/IL-4/IL13) under vitamin D deficiency, MS4A2’s role is protective and vitamin D-dependent." (PMID 40927566, 2025). "Our data highlight the specific regulation of the IL-2/STAT5 pathway by vitamin D. Vitamin D deficiency and impaired Vdr signaling caused elevated IL-2 production by Th2 cells, leading to high IL-13 production." (PMID 38567749, 2024). "Vitamin D has been shown to downregulate allergen induced expression of IL-13, suggesting an immunoregulatory role and reduction of airway inflammation and hyperreactivity, and vitamin D deficiency has been associated with asthmatic symptoms, including wheezing and respiratory infections." (PMID 35215452, 2022). "This IL-13 production solely in the vehicle-treated VDD mice might be the consequence of low levels of circulating 1α,25(OH)2D3 with vitamin D deficiency, hampering vitamin D to inhibit LPS-induced IL-13 as previously reported." (PMID 35351141, 2022). "Further research could also consider the effect of TLR7 on other pathways involved in the amplification of the Th2 response, such as IL-13, IL-31, and IL-33 cytokines, vitamin D deficiency, and changes in the lung microbiome, in the context of chronic respiratory disease." (PMID 39769461, 2024). "Vitamin D deficiency shifts this system toward a pro-inflammatory state that favors Th1 and Th17 activation and increased expression of TNF, IFNγ, and IL-17, as well as elevated expression of pro-inflammatory Il-4, IL-5 and IL-13, and gut barrier dysfunction." (PMID 32093192, 2020). "Again, vitamin D deficiency enhanced the capacity of ADLN cells to proliferate and secrete cytokines like IL-5 and IL-13 (data not shown)." (PMID 23826346, 2013).
vitiligo (9 papers, 2013 to 2025). Generalized well circumscribed patches of leukoderma that are generally distributed over symmetric body locations and is due to autoimmune destruction of melanocytes. "Remarkably, many of the increased proteins in patients achieving F-VASI50 were interleukins such as IL-20 and Th2 linked cytokines IL-5 and IL-13 for which no major role in vitiligo has previously been described." (PMID 38715599, 2024). "Interestingly, they also observed significantly decreased levels of IL-6, TNF-α, IFN-γ, and IL-13 in sera of vitiligo mice models." (PMID 33613564, 2020). "In addition, a variety of cytokines secreted by T helper cell subsets- Th1 (IFN-γ, TNF-α, IL-2) and Th2 (IL-4, IL-10, IL-13) not only exacerbate autoimmune responses but also perpetuate the vicious cycle of immune dysfunction, ultimately leading to the clinical manifestations of vitiligo." (PMID 40725033, 2025). "Meanwhile, there is mounting evidence that the immunological milieu of vitiligo is also characterized by cytokines connected to other Th2 cell responses, such as IL-4, IL-5, IL-10, IL-13, and IL-31, rather than just Th1 cells and related cytokines (IFN-γ, TNF-α, and IL-2)." (PMID 38695020, 2024). "Other groups have reported that IL10, IL13, IL17A, and IL21 are increased in vitiligo, though we did not observe this in our case series study." (PMID 33384688, 2020).
bronchiolitis (8 papers, 2009 to 2025). Inflammation of the bronchioles characterized by swelling of the bronchioles and mucus accumulation. "Infants hospitalized with HRSV-caused bronchiolitis had high levels of IL-13 and IL-33, which were associated with the need for ventilation." (PMID 37239461, 2023). "It should be noted that certain polymorphism, such as IL-4 590T and IL-4Ralpha R551 alleles, could be linked to more sereve bronchiolitis and the IL-13 Gln allele may identify children at risk for persistent wheezing as shown in RSV affected children." (PMID 19781072, 2009). "The bronchiolitis group serum IL-5, IL-9, IL-13, IL-33, TSLP protein levels were higher than the normal control group." (PMID 33514798, 2021). "Mixed Th1/Th2-type immune responses (including eosinophils, neutrophils, and both IL-13- and IFN-γ-producing CD4+ T cells) are also a feature of vaccine-enhanced RSV disease in mice and of human bronchiolitis (44, –, 46), indicating that dysregulation is the hallmark of RSV disease." (PMID 23926350, 2013). "The expression level of IL-13 in this study was higher than that of the normal control group, suggesting that IL-13 may be involved in airway inflammation and AHR in children with bronchiolitis in the acute phase." (PMID 33514798, 2021).
cutaneous leishmaniasis (8 papers, 2010 to 2024). Leishmaniasis affecting the skin. "Although IL-4 and IL-13 are associated with development of type 2 immune responses in models of cutaneous leishmaniasis, there are many conflicting reports of both IL-4 and IL-13 having opposite roles to play in VL." (PMID 22511870, 2012). "IL-13 activates eosinophils and promotes the development of alternatively activated macrophages, which have been shown to promote disease progression in cutaneous leishmaniasis." (PMID 38359037, 2024). "To test the role of IL-4 or IL-13 for the action of PSG during cutaneous leishmaniasis we co-infected WT and IL-4Rα-/- BALB/c mice with a low dose of L. mexicana metacyclics in the presence or absence of PSG." (PMID 29352310, 2018). "We investigated nine SNVs (SNV1rs1881457A>C, SNV2rs1295687C>G, SNV3rs2069744C>T, SNV4rs2069747C>T, SNV5rs20541A>G, SNV6rs1295685A>G, SNV7rs848A>C, SNV8rs2069750G >C, and SNV9rs847T>C) spanning the entire IL13 gene in patients with L. guyanensis cutaneous leishmaniasis (Lg-CL)." (PMID 37908348, 2023). "Accordingly, our previous study in CD11ccreIL-4Rα−/lox mice, which have impaired IL-4 receptor alpha (IL-4Rα) expression on CD11c+ cells including DCs, confirmed a protective role for IL-4/IL-13-responsive DCs in replication and dissemination of parasites during cutaneous leishmaniasis." (PMID 32039054, 2019). "To identify the source of TSLP during cutaneous leishmaniasis, we sorted CD45+ hematopoietic and CD45- nonhematopoietic cells from the ears of either naïve or infected WT and eoCre: Il4/13f/f mice having a selective deficiency of IL-4/IL-13 in eosinophils." (PMID 38030609, 2023).
cystic fibrosis (8 papers, 2012 to 2025). Autosomal recessive disorder caused by pathogenic variants in the CFTR gene (cystic fibrosis transmembrane conductance regulator), which encodes a chloride and bicarbonate channel expressed in epithelial cells, and follow the diagnosis criteria. "We showed here that instillation of “sterile” agarose beads in a rat biofilm model, extensively used in the field of cystic fibrosis research, activates the same Th2 cytokines (IL-5 and IL-13) and Th2 innate cells (eosinophils and Arg1+ M2 macrophages) as observed in human CF patients." (PMID 28680858, 2017). "Both SERPINB4 and CTSC are up-regulated in IL13 treated human primary bronchial epithelial cells on air liquid interface culture, and PLA2G4A is more active in bronchial explants from individuals with cystic fibrosis." (PMID 22676183, 2012).
Hyperglycemia (8 papers, 2017 to 2025). An increased concentration of glucose in the blood. "While IL-13 inhibits gluconeogenesis in mouse experiments, a global IL13 knockout produces hyperglycemia, hepatic insulin resistance, and systemic metabolic dysfunction in mice of a C57BL/6 genetic background." (PMID 37629063, 2023). "The therapeutic application of IL-13 improves post-ischemic gluconeogenesis and hyperglycemia in a rat model." (PMID 37629063, 2023). "It indicates that only women with prior GDM, characterized by hyperglycemia and impaired insulin secretion in our study, exhibited unique IL13 and RELA overexpression profiles." (PMID 36499008, 2022). "In streptozotocin-induced T1D in wild-type mice, Schistosoma mansoni infection inhibits the breakdown of pancreatic islets and hyperglycemia through increased Arg-1 and Ym1 expression rather than through processes that rely on Treg, IL-4, IL-13, and IL-10." (PMID 40299229, 2025).
mastitis (8 papers, 2013 to 2024). Inflammation of breast tissue during lactation or postpartum due to an obstructed duct or infection. "IL-13 in bovine udder, milk, and association with mastitis has been poorly studied." (PMID 35335696, 2022). "This might be crucial to hold readiness for both inflammation risk and tissue damage in healthy cows by both IL-4 and IL-13, but only by IL-4 in mastitis-affected cows." (PMID 35335696, 2022). "In general mastitis cases, immunoreactivity was more pronounced for IL-4, IL-6, IL-12, IL-13, IL-17A, TNF-α, and IFN-γ." (PMID 39195804, 2024). "In mastitis cases, immunoreactivity was more pronounced for IL-4, IL-6, IL-12, IL-13, IL-17A, TNF-α, and IFN-γ." (PMID 35335696, 2022). "IL-13 immunoreactivity in clinical mastitis was almost undetectable." (PMID 35335696, 2022). "Its abundance is negatively correlated with the levels of inflammatory cytokines (IL-12, IL-13 and IFN-γ).We found this genus in milk samples and it decreased in abundance in the mastitis group, indicating that the body was at an inflammatory level with a large increase in inflammatory cells." (PMID 37420170, 2023). "Mean IL-13 immunoreactive cell counts (%) and overall immunoreactivity for IL-13 in clinical mastitis-affected cows were almost none." (PMID 35335696, 2022). "In summary, in clinical mastitis-affected cows, immunoreactive cell mean counts in milk increased for IL-4, IL-6, IL-12, and IL-17A and remained nearly absent for IL-13." (PMID 35335696, 2022). "However, mean IL-13 immunoreactive cell numbers (%) were low in healthy animals and almost absent in animals affected by mastitis." (PMID 35335696, 2022). "However, the immunological profile of milk samples revealed remarkable differences, mainly related to the components of the adaptive immune system, depending on the etiological agent of mastitis, with IL10 and IL13 being detected in the samples from SAM cases but not in those of AM cases." (PMID 35079053, 2022).